HJV (hemojuvelin BMP co-receptor)
Description:
Acts as a bone morphogenetic protein (BMP) coreceptor. Through enhancement of BMP signaling regulates hepcidin (HAMP) expression and regulates iron homeostasis.
Synonyms: HFE2; RGMC; JH; HFE2A; hemojuvelin; haemojuvelin
Tractability: Antibody: its Gene Ontology location is reachable by antibodies, with high confidence; UniProt places it where antibodies can reach, with medium confidence; UniProt predicts a signal peptide or a membrane-spanning region.
Gene: Protein-coding gene on chromosome 1 (146,017,468 to 146,036,746, reverse strand). Ensembl gene ENSG00000168509.
Subcellular location: Cell membrane
Pathways (Reactome):
Developmental Biology: Netrin-1 signaling
Gene Ontology:
Molecular function: BMP binding; BMP receptor activity; coreceptor activity; protein binding; signaling receptor binding; transferrin receptor binding
Biological process: activin receptor signaling pathway; BMP signaling pathway; cellular response to BMP stimulus; multicellular organismal-level iron ion homeostasis; positive regulation of transcription by RNA polymerase II; protein autoprocessing; intracellular iron ion homeostasis; negative regulation of transcription by RNA polymerase II
Cellular component: BMP receptor complex; extracellular region; HFE-transferrin receptor complex; plasma membrane; plasma membrane protein complex; cell surface
Genetic constraint (gnomAD): Loss-of-function variants: 23 observed, 28.38 expected, observed/expected ratio (o/e) 0.81, 90% interval 0.58 to 1.15. The upper end of that interval is the gene's LOEUF score, 1.15, which puts it in group 5 of 6, group 1 being the genes least tolerant of losing a copy. Missense variants: 563 observed, 583.17 expected, observed/expected ratio (o/e) 0.97, 90% interval 0.9 to 1.03. Synonymous variants: 223 observed, 232.89 expected, observed/expected ratio (o/e) 0.96, 90% interval 0.86 to 1.07.
Gene-disease validity (ClinGen):
ClinGen rates the evidence that HJV causes each of these diseases.
hemochromatosis type 2A (autosomal recessive): Definitive. Any hemochromatosis type 2 in which the cause of the disease is a mutation in the HJV gene.
Homologues: Orthologues: chimpanzee HJV (99% identical), macaque HJV (98% identical), rabbit HJV (93% identical), pig HJV (93% identical), guinea pig HJV (89% identical), mouse Hjv (87% identical), rat Hjv (87% identical), dog HJV (69% identical), tropical clawed frog hjv (53% identical), zebrafish hjv (44% identical), Caenorhabditis elegans drag-1 (23% identical). Paralogues in human: RGMA (46% identical), RGMB (43% identical).
Diseases named in the same sentence as HJV in open-access papers:
HJV is named in the same sentence as 47 diseases in open-access papers, as found by Europe PMC text mining. Sharing a sentence is not in itself a finding about the gene and the disease. The quoted sentences say what the papers report.
hemochromatosis (38 papers, 2004 to 2025). A disorder of iron metabolism characterized by a triad of HEMOSIDEROSIS; LIVER CIRRHOSIS; and DIABETES MELLITUS. "It elucidates diverse inheritance patterns and clinical manifestations by exploring mutations in critical genes such as HFE (hemochromatosis), HJV (hemojuvelin), HAMP (hepcidin antimicrobial peptide), TfR2 (transferrin receptor 2), and FP (ferroportin)." (PMID 39114232, 2024). "Previous studies have reported that HJV gene polymorphisms act as genetic modifiers in the hereditary hemochromatosis (HH) phenotype." (PMID 37006987, 2023). "A crucial component of hepatocyte BMP signaling is the hemojuvelin protein; in humans, mutations in the HJV gene can result in juvenile hemochromatosis that is clinically undistinguishable from hemochromatosis caused by mutations of the hepcidin gene itself." (PMID 33800732, 2021). "Pathogenic mutations in the HJV gene cause hemochromatosis in an autosomal recessive hereditary pattern." (PMID 31286966, 2019). "Mutations in the genes transferrin receptor 2 (TfR2), ferroportin, and hemojuvelin (HJV) can also cause hemochromatosis." (PMID 30360383, 2018). "These molecules include HFE (HLA2-linked hemochromatosis gene), transferrin receptor 2 (TfR2), hemojuvelin (HJV) and bone morphogenetic protein (BMP)." (PMID 24731443, 2014). "Recent data confirm the involvement of genes that encode proteins HFE (hemochromatosis), HJV (haemojuvelin), TfR2 (transferrin receptor), SLC40A1 (ferroportin) in maintaining iron homeostasis by stimulating the production of hepcidin." (PMID 24146699, 2013). "In juvenile hemochromatosis, mutations in HJV gene have as a result the decrease of hepcidin expression and the subsequent iron overload." (PMID 19238200, 2009). "A variety of HJV coding region mutations occur in homozygous or compound heterozygous configuration in persons with juvenile or adult-onset hemochromatosis phenotypes." (PMID 15610558, 2004). "Homozygosity or compound heterozygosity for coding region mutations of the hemojuvelin gene (HJV) in whites is a cause of early age-of-onset iron overload (juvenile hemochromatosis), and of hemochromatosis phenotypes in some young or middle-aged adults." (PMID 15610558, 2004). "However, we observed that R288 is a particularly conserved amino acid and that missense change to tryptophan (R288W) causes a severe hemochromatosis disease 31, highlighting the relevance of this residue for HJV function." (PMID 25704252, 2015). "Non-HFE hemochromatosis is less frequent and includes hepcidin-deficient hemochromatosis, such as hemojuvelin (HJV type 2A), hepcidin (HAMP type 2B), and TRF2-related hemochromatosis (type 3)." (PMID 39323676, 2024). "The hereditary hemochromatosis-associated membrane proteins HFE, TFR2, and HJV are required for adequate hepatic expression of the iron hormone hepcidin." (PMID 35163229, 2022). "HJV was found to be a co-receptor for BMP, as mutations in Hjv gene results in hemochromatosis, a disease manifested by iron overload." (PMID 33036384, 2020). "The identification of HJV and HAMP as juvenile hemochromatosis genes led to the discovery of HJV as a BMP co-receptor, and the establishment of the major role of the BMP/SMAD signaling pathway in hepcidin regulation." (PMID 30420953, 2018). "The severe phenotype of HJV knockout mice and juvenile hemochromatosis patients is in keeping with the important role of HJV as a BMP co-receptor and with the importance of the BMP-signaling pathway in basal hepcidin transcription." (PMID 24639653, 2014). "Mutations within several genes have been associated with HH, these include hemochromatosis (HFE), hemojuvelin (HJV), transferrin receptor 2 (TfR2), and hepcidin (HAMP)." (PMID 20670400, 2010). "As hemochromatosis can also be caused by other mutation in the HFE gene or so called non-HFE hemochromatosis genes (HJV, HAMP, TFR2), homozygosity for p.Cys282Tyr is neither sufficient nor necessary for the diagnosis hemochromatosis." (PMID 30514216, 2018).
hemochromatosis (continued). "In a mouse model of hemochromatosis, mutations in a BMP6 co-receptor (i.e., HJV) were found to result in an accumulation of iron in mouse retinal tissues and upregulation of BMP6 along with upregulation of VEGF that resulted in subsequent abnormal vascularization of the retina." (PMID 30255811, 2018). "We evaluated the genomic DNA of 241 Alabama white and 124 African American adults who reported no history of hemochromatosis or iron overload to detect HJV missense mutations I222N and G320V using polymerase chain reaction-restriction fragment length polymorphism (PCR-RFLP) technique." (PMID 15610558, 2004). "HJV (hemojuvelin) is a BMP co-receptor and enhancer of iron signaling to hepcidin, and its disruption leads to severe hemochromatosis in humans and mice." (PMID 33096618, 2020).
iron overload (32 papers, 2004 to 2025). "The severe form of iron overload is called juvenile hemochromatosis, resulting from mutation in the hemojuvelin (HJV) gene." (PMID 38555503, 2024). "Inactivation of the HJV gene causes juvenile hemochromatosis, an early onset variant of hereditary hemochromatosis, and Hjv−/− mice recapitulate the iron overload phenotype." (PMID 36982241, 2023). "Hemojuvelin (HJV) enhances signaling to the iron hormone hepcidin and its deficiency causes iron overload, a risk factor for hepatocellular carcinoma (HCC)." (PMID 35194137, 2022). "Hemojuvelin (HJV) functions as a BMP coreceptor and is critical for hepcidin expression in response to iron loading, as shown by the severe iron overload (juvenile hemochromatosis) developed by patients with mutations in HJV." (PMID 35628152, 2022). "Hemojuvelin (HJV) is a bone morphogenetic protein co-receptor that has been identified as a main upstream regulator of hepcidin expression; HJV mutations are associated with a severe form of iron overload (Juvenile haemochromatosis)." (PMID 22998440, 2012). "HJV coding region mutations have also been identified recently in African American primary iron overload and control subjects." (PMID 15610558, 2004). "Our attention specifically encompassed the HJV-TMPRSS6-NEO1 axis, providing a broader understanding of iron metabolism disturbances, which frequently predispose children with acute leukemias to iron overload and adverse clinical outcomes." (PMID 40805193, 2025). "In terms of genetics, different types of hereditary hemochromatosis are caused by mutations in the HFE, hepcidin (HAMP), hemojuvelin (HJV), ferroportin (SLC40)A1, and transferrin receptor 2 (TfR2) genes that correspond to genetic disorders of iron overload." (PMID 32635533, 2020). "The severity of iron overload increases in the order from HFE-/- to TFR2-/- to HJV-/- or HAMP-/-." (PMID 30608934, 2019). "Many patients with JH have mutations in the HJV gene, which encodes hemojuvelin, and mice lacking hjv develop an iron-overload phenotype." (PMID 18384687, 2008). "Although a lot of genes are involved in these pathways, we chose to measure FPN1, TfR1, TfR2 and HJV mRNA expression because mutations in Tfr2, HJV, and FPN1 prevent appropriate hepcidin response to iron, allowing increased absorption of dietary iron, and eventually iron overload." (PMID 29065180, 2017). "Inactivation of the HJV (hemojuvelin), a BMP co-receptor, leads to early onset juvenile hemochromatosis, characterized by more severe iron overload." (PMID 31442254, 2019). "Other mutations, such as H63D in HFE or mutations in non-HFE genes like HAMP, HJV, TFR2, and SLC40A1 (FPN1), also contribute to iron overload but tend to have a variable clinical impact." (PMID 39323676, 2024). "Of the 32 patients with primary iron overload (23 were males and 9 were females), non-HFE variants were detected in 31 (31/32, 97%), including 8 pathogenic variants in HJV, 7 pathogenic variants in SLC40A1, 8 likely pathogenic variants in SUGP2 and 5 likely pathogenic variants in DENND3 cases." (PMID 34583728, 2021). "Moreover, there are other point mutations including H63D and non-HFE gene mutations such as hemojuvelin (HJV), hepcidin (HAMP), transferrin receptor 2 (TfR2), and ferroportin (SLC40A1) that are shown to cause milder degree of iron overload." (PMID 24024049, 2013).
juvenile hemochromatosis (24 papers, 2004 to 2025). "Hereditary hemochromatosis type 2A (juvenile hemochromatosis) is a rare autosomal recessive disorder caused by mutations in the HJV gene." (PMID 40979821, 2025). "Two less common subtypes, termed “juvenile hemochromatosis” (JH), are caused by pathogenic variants in the hemojuvelin gene (HJV type 2a HH) or hepcidin gene (HAMP type 2b HH), with onset frequently in the second to third decade of life." (PMID 39450139, 2024). "Type 2 hemochromatosis, or juvenile hemochromatosis, results from mutations in the HJV (Hemojuvelin) gene (Type 2A) or the HAMP (Hepcidin) gene (Type 2B)." (PMID 39323676, 2024). "Hemochromatosis type 2, also defined as juvenile hemochromatosis, is divided into type 2A (mutation of the hemojuvenile gene, HJV, MIM #602390) and type 2B (mutation of the hepcidin antimicrobial peptide gene, HAMP, MIM #613313)." (PMID 27363994, 2016). "The characterization of hemojuvelin (HJV), the protein mutated in type 2A hemochromatosis, as Bone Morphogenetic Protein (BMP)-coreceptor, functionally linked the BMP-Sons of Mothers Against Decapentaplegic (SMAD) pathway to hepcidin and iron regulation." (PMID 25860887, 2015). "The centrality of this regulatory pathway was confirmed by the finding that hemojuvelin (HJV), which is mutated in severe juvenile hemochromatosis, acts as a co-receptor of the BMP/SMAD pathway in the liver." (PMID 24808863, 2014). "Juvenile hemochromatosis (JH) or type 2 hereditary hemochromatosis, is a rare condition affecting about 1 in 4.8 million people and results from autosomal recessive loss-of-function mutations in either the HJV (type 2a) or HAMP (type 2b) genes." (PMID 29373985, 2018). "Type 2 HH, known as juvenile hemochromatosis, is caused by variants of the hepcidin (HAMP) and hemojuvelin (HJV) genes, while type 3 HH is related to variants of the TfR2 (TFR2) gene." (PMID 34067164, 2021). "Juvenile hemochromatosis is the name of the HH types 2a and 2b (OMIM #602390 and #613313) that are caused by mutations in the hemojuvelin (HJV) protein (coded by the HFE2 gene) and in the iron hormone hepcidin (coded by the HAMP gene) (OMIM *608374 and *606464)." (PMID 34946929, 2021). "Gene mutations affecting the gene HFE2, which encodes HJV protein, result in the absence of hepcidin and cause juvenile hemochromatosis." (PMID 21936923, 2011).
hereditary hemochromatosis (14 papers, 2013 to 2025). An inherited metabolic disorder characterized by iron accumulation in the tissues. "For example, hereditary hemochromatosis (HH), which is caused by mutations in the genes that encode hemojuvelin (HJV, or HFE2) and hepcidin (HAMP) are associated with excessive iron absorption and iron-related toxicity, particularly in juvenile HH." (PMID 28657578, 2017). "Mutations in hemojuvelin (HJV) are the most common cause of the juvenile-onset form of the iron overload disorder hereditary hemochromatosis." (PMID 24860505, 2014). "In hepatocytes, HJV is a positive regulator of hepcidin expression, and its mutations cause a juvenile form of hereditary hemochromatosis, a disease characterized by iron overload due to uncontrolled iron entry into the circulation consequent to reduced hepcidin production and FPN1 stabilization." (PMID 36835406, 2023). "Hereditary hemochromatosis is caused by mutations in iron regulatory genes, including HAMP (hepcidin gene), HFE (hemochromatosis gene), TFRC (transferrin receptor), HJV (hemojuvelin), and SLC40A1 (ferroportin), and heterozygous mutations in BMP6 pro-peptide." (PMID 40871742, 2025). "HJV is essential for BMP6 signalling because the disruption of the protein, as occurs in the juvenile form of the iron loading disorder, haemochromatosis, leads to the complete loss of hepcidin production." (PMID 34611951, 2021). "Additionally, hepcidin expression is impaired when HJV, HFE, and TFR2 are mutated, as in hereditary hemochromatosis." (PMID 36835406, 2023). "Genetic variants leading to excess body iron occur mainly in the haemochromatosis (HFE) gene but are also seen in hepcidin (hepcidin antimicrobial peptide (Hamp)), transferrin receptor 2 (TFR2), solute carrier family 40 member 1 (SLC40A1), haemojuvelin (HJV) and transferrin (TF) genes." (PMID 32609760, 2020). "A liver biopsy showed an almost normal liver specimen with a slight deposition of iron in 2-3% of hepatocytes, and a genetic examination of hereditary hemochromatosis revealed no typical mutations in HFE, TFR2, HJV, HAMP, or SLC40A1." (PMID 36968338, 2023). "Non-HFE hereditary hemochromatosis is mostly associated with pathological mutations of proteins, which orchestrate iron homeostasis, such as hepcidin (HAMP), ferroportin (FPN), hemojuvelin (HJV) and transferrin receptor 2 (TFR2)." (PMID 35453939, 2022).
iron deficiency (9 papers, 2014 to 2025). "IRIDA is one type of iron-deficiency anemia due to mutation of the transmembrane serine protease 6, which cleaves HJV and, in turn, inhibits BMP-6-induced hepcidin expression." (PMID 34679725, 2021). "Interestingly, BMP/HJV signaling is necessary for hepcidin production and iron regulation, and could contribute to PH patients’ frequent iron deficiency." (PMID 40569693, 2025). "On the other hand, in support for the in vivo processing of HJV by MT2, we did previously report cleavage of liver HJV, coupled with increased content of MT2, in rats with severe iron deficiency anemia." (PMID 33800732, 2021). "In iron deficiency, the regulation pathway for iron status includes activity of the BMP/HJV and HFE/TFR2 complex." (PMID 24894955, 2014). "HJV is a glycophosphatidylinositol- (GPI-) anchored protein; MT-2 cleavage the membrane HJV (m-HJV) to a form of soluble HJV (s-HJV) to decreases the affinity for BMP6; thus, the MT-2 expression increases during iron deficiency." (PMID 32454791, 2020). "Despite hemojuvelin (HJV) acting as a BMP co-receptor in the BMP-signaling pathway that modulates hepatic hepcidin expression, the iron deficiency (FeD) did not alter hepatic Hfe2 mRNA levels compared with those of the control." (PMID 27551308, 2016).
hepatoma (4 papers, 2012 to 2022). "Biochemical evidence supports these data by demonstrating that HJV, HFE, and TfR2 form a membrane associated complex in human hepatoma cells." (PMID 23917168, 2013). "The direct regulation of hepcidin and HJV expression by pro-inflammatory cytokines was also examined in vitro using a human hepatoma cell line (HuH7)." (PMID 22998440, 2012). "Although it is known that BMP2, BMP4, and BMP6 are endogenous ligands for HJV in human hepatoma cells, and HJV uses selectively the BMP type II receptors BMPRII and ActRIIA, specific roles of individual BMP type II receptors in iron metabolism have yet to be investigated." (PMID 23917168, 2013). "In a recent study using the human hepatoma cell line (HuH-7) and transient expression systems it was shown that HFE, TFR2 and hemojuvelin (HJV) form a complex on the membrane, and the formation of this complex is required for the regulation of hepcidin." (PMID 24155934, 2013).
Duchenne muscular dystrophy (3 papers, 2022 to 2025). Duchenne muscular dystrophy (DMD) is a neuromuscular disease characterized by rapidly progressive muscle weakness and wasting due to degeneration of skeletal, smooth and cardiac muscle. "In 2019, it was revealed for the first time that the iron metabolism regulatory molecule Hemojuvelin (HJV or HFE2) is a protective gene that inhibits the occurrence of Duchenne muscular dystrophy and senile muscle atrophy." (PMID 36615225, 2022). "Furthermore, HJV expression is significantly reduced in the muscles of patients with Duchenne muscular dystrophy (DMD), mdx (DMD model) mice, and aging humans and mice." (PMID 40076640, 2025).
iron deficiency anemia (3 papers, 2013 to 2021). "Expression of hepcidin is homeostatically regulated by anaemia, hypoxia, inflammation, and also by the function of the hemochromatosis protein (HFE), hemojuvelin (HJV) and TfR2, as indicated by their mutation that decreased hepcidin expression." (PMID 24078156, 2013).
melanoma (2 papers, 2019 to 2023). A malignant, usually aggressive tumor composed of atypical, neoplastic melanocytes. "As seen for RGMA and RGMB, predicted mutations of RGMC/HJV are found in many different cancers, with transcripts encoding mutant proteins being detected in 25% of prostate cancers, 10% of ovarian carcinomas, and 8.4% of melanomas (see Results)." (PMID 30746893, 2019). "Then, we identified 9 LR pairs (“BMP6- > HJV” 、"CCL8- > ACKR4” 、"DLL3- > NOTCH3"、"DSC3- > DSG3"、"GHRH- > GHRHR” 、"LRRC4B- > PTPRF"、"SEMA4D- > PLXNB1"、"SFRP1- > FZD6"、"UCN- > CRHR1′′) as key LR pairs in melanoma prognosis through Lasso Cox regression and Multiple Stepwise Regression." (PMID 36777724, 2023).